IL21 (interleukin 21)
Diseases named in the same sentence as IL21 in open-access papers (continued):
Sharing a sentence is not in itself a finding about the gene and the disease.
tumor (continued). "To explore the role of IL-21 in promoting the proliferation of EBV-positive DLBCL cells in vivo, we conducted a complement of experiments and evaluated the in vivo efficacy of IL-21 in EBV-positive DLBCL xenograft tumour experiments." (PMID 32704112, 2020). "This study is now focused on tumor-infiltrating T cells, particularly those expressing IL21 and IL26, as these are major cytokines produced by tumor-promoting Th-17-like cells." (PMID 31948053, 2020). "Regardless what culture medium was used, IL-15low+IL-21 stimulated NK cells were able to quickly infiltrate and completely lyse the tumor spheroids." (PMID 31849984, 2019). "We subsequently found that strong tumor infiltration by IL-21-producing CD8+CXCR5+ T cells led to the accumulation of IL-21+ cells within the peritumoral stroma and that this accumulation correlated negatively with the TNM staging of the patients." (PMID 31663864, 2019). "Consistently, in B16F10 tumor-bearing mice, the frequency of IL-6+, IL-21+ and IL-10+ CD4+ T cells in the draining lymph node and spleen were also increased." (PMID 31300052, 2019). "For example, MSCs were reported to be engineered to highly express IL-12, IL-21 or IFNγ to enhance tumor targeting." (PMID 31320999, 2019). "In the majority of patients (221/264), tumor cells expressed the receptor for IL-21 (IL-21R) and also a downstream target of IL-21, Blimp-1 (199/264)." (PMID 31540511, 2019). "Tumor-directed T cells expanded in IL-21 conditional media showed enhanced antitumor efficacy in a B16-melanoma mouse model." (PMID 31379876, 2019). "On a molecular level, invasiveness of tumor cells, a key factor required for metastasis, was affected by IL-21." (PMID 31540511, 2019). "After dendritic cell maturation and onset of T cell immune response, IL-21 promotes and maintains the activity of tumor-specific T cells." (PMID 31467912, 2019). "We found that numbers of IL-21-producing CD8+CXCR5+ T cells were significantly higher within HCC tumor tissue than in the matched blood and peritumoral liver tissue or in healthy blood samples." (PMID 31663864, 2019). "For Bregs, granzyme B expressing Bregs, induced by tumor cells and IL-21, react to tumor cells and promote tumor immune escape." (PMID 31662750, 2019). "Because IL-21 plays a critical role in regulating immunoglobulin production, we investigated the possible effects of tumor-infiltrating CD8+CXCR5+ T cells on B cells." (PMID 31663864, 2019). "Here we report a novel interleukin (IL)-4 vs. IL-21 ICR (4/21 ICR) that enhanced CAR-T cell potency in IL-4+ tumor milieu via a different working-mechanism from 4/7 ICR." (PMID 31379876, 2019). "As a possible underlying cellular process, we observed an enhanced capacity of IL-21 treated tumor cells to migrate into a 3-D gel matrix, a method imitating invasive cell growth." (PMID 31540511, 2019). "TH17 cells, on the other hand, produce IL-17A, IL-17F, IL-21, and IL-22, which promote tumor growth by favoring antimicrobial tissue inflammation." (PMID 31906017, 2019). "We found that IL-21-producing CD8+CXCR5+ T cells strongly infiltrate HCC tumor tissue as compared to peritumoral tissue or peripheral blood from the same patients or blood from healthy donors." (PMID 31663864, 2019). "Vaccination with irradiated cells overexpressing GM-CSF or IL-21 alone significantly inhibited tumor growth and led to significantly more CD4+ CD8+ T cells and fewer CD4+ Foxp3+ T cells in the spleen and xenograft." (PMID 31467912, 2019). "IL-21-expressing TRUCKs mediated the best overall tumor immunity in mice, demonstrated by their capacity to increase survival." (PMID 30842774, 2019). "Numerous animal tumor models have demonstrated broad anti-tumor activity for various cytokines, including GM-CSF, IL-2, IL-7, IL-12, IL-15, IL-18 and IL-21." (PMID 31856922, 2019). "Human CAR-T cells engineered to express IL-21, efficiently eliminated tumor cells with long-term persistence in immunodeficient mice." (PMID 31379876, 2019).
tumor (continued). "For both the vehicle control and IL-21 group, the same number of chick embryos survived until day 17 (13/50) when embryos were euthanized and the tumor was resected." (PMID 31540511, 2019). "The combination of both miR-200c with IL-21-secreting human umbilical cord MSCs exerts an inhibitory role not only in the tumor growth and metastasis but also in the epithelial-mesenchymal transition (EMT) in epithelial ovarian cancer." (PMID 31386624, 2019). "We demonstrated that large numbers of IL-21-producing CD8+CXCR5+ T cells accumulate within HCC tumor tissue." (PMID 31663864, 2019). "IL-2, IL-15 and IL-21 conditioning of total TILs from the resected PanTT26 tumour piece (which includes the TLS) was enriched for CD8+ T cells, as confirmed in the cytotoxicity assay performed with the autologous tumour cell line." (PMID 30377343, 2019). "IL-21/IL-7-treated cells have increased proliferation and production of inflammatory cytokines, directing improved lysis of tumor cells." (PMID 30842774, 2019). "We found that the frequency of IL-21-producing CD8+CXCR5+ T cells was higher in HCC tumor tissue than in peritumoral tissue or peripheral blood from the same patients or in blood from healthy donors." (PMID 31663864, 2019). "These stronger effects positively correlated with enhanced infiltration by CD4+ and CD8+ effector T cells: numbers of CD4+, CD8+, and IFN-γ+ CD8+ T cells in blood and tumor were higher in the GM-CSF/IL-21 group than in the other groups." (PMID 31467912, 2019). "From the same cases, fresh tumor tissue was cultured in medium containing IL-2, IL-15 and IL-21 to cultivate TILs, and percentage of TCR gamma-delta T-cells (CD3+ TCR γδ+) and NK cells (CD3- CD56+ CD16+) was analyzed by flow cytometry (FC)." (PMID 30400835, 2018). "Of interest, B cells stimulated by IL-21 are able to kill tumor cells by producing granzyme B. B cells also facilitate CD4+ T cell memory function and CD8+ T cells proliferation." (PMID 29850009, 2018). "The whole blood of patients with cancer was also exposed to IL-2, IL-15 and IL-21 in culture, which we have previously reported to have a pronounced effect on amplifying tumor-directed T-cell responses." (PMID 29970101, 2018). "Fresh tumor from primary (P) and peritoneal metastasis (PM) cancer lesions and colon tissue (C) were cultured in medium containing IL-2, IL-15 and IL-21." (PMID 30400835, 2018). "We identified an association of TAA-reactive T-cells (defined by IFN-γ production) in correlation with the histopathological grading of the tumor and T-cells cultured with IL-2/IL-15 and IL-21." (PMID 29058035, 2018). "The fusion with cytokines like IL-21 or IL-15 can activate T and NK cell immunity in the tumor proximity and help tumor clearance." (PMID 30254634, 2018). "Neo-antigen load also correlated with increased expression of IL23A, IL21, and IL17RA, all of which are players in the Th17 T cell pathway, which is implicated in both tumorigenesis as well as the anti-tumor immune response." (PMID 29487705, 2018). "In this context, IL-21 acts a critical opposing force, specifically limiting tumour-mediated FOXP3 induction and preventing suppression of the naïve T cell response." (PMID 28239749, 2017). "Consistent with these signaling differences, analysis of the effects of IL-2 and IL-21 on the anti-tumor activity of CD8+ T cells revealed that these cytokines induced distinctive transcriptional profiles, with associated differences in disease outcome." (PMID 29123649, 2017). "IL-21 is known to promote anti-tumour immunity due to its ability to promote T cell responses and counteract Treg-mediated suppression." (PMID 28239749, 2017). "The absence of miR-21 also reduced the expression of inflammatory cytokines (IL-6, IL-23, IL-17A and IL-21) and attenuated the proliferation of tumour cells." (PMID 28099146, 2017).
tumor (continued). "Other protocols that improve NK cell development and function by adding methylprednisolone to induce preferential differentiation of HSCs toward NK cells or by adding IL-12 or IL-21 to promote NK cell maturation and cytotoxicity to tumor cells are developing." (PMID 28824650, 2017). "Whereas IL-2 enhanced CD8+ T cell proliferation and effector function, IL-21-treated cells exhibited a central memory phenotype, with greater persistence of the cells and higher anti-tumor activityin vivo." (PMID 29123649, 2017). "Upon investigating the anti-cancer properties of TH9 cells differentiated in the presence of IL-1β, we noted that IL-21 was critical in driving the anti-tumor effects of TH9 cells upon adoptive transfer in vivo." (PMID 27832300, 2017). "In the study fluorescent-labeled gene nanoparticles consisting of gene fragments of IL-21, a cytokine involved in lymphocyte activation and tumor suppression, and NKG2D were developed and intravenously injected into mice pretransplanted with tumors." (PMID 28919894, 2017). "Even at a decreased dose of lymphocytes (10 million cells/mouse) the IL-2, IL-21, IL-2/21, IL-7/15 and IL-7/15/21 groups were significantly better at slowing or decreasing tumor growth than the control or the cyclophosphamide-alone groups (all p < 0.0001)." (PMID 28146052, 2017). "In the context of cancer, a crucial finding has been that IL-21 reduces the frequency of human FOXP3+ Treg cells by greater than 10-fold during tumour antigen stimulations." (PMID 28239749, 2017). "Overall, these results indicate that in the context of lung adenocarcinoma, colon carcinoma, and melanoma, TH9 cells promote activation of adaptive anti-tumor immune responses through their secretion of IL-9 and IL-21." (PMID 27832300, 2017). "In contrast, anti-inflammatory cytokines (IL-2, IL-15, and IL-21) usually activate the antitumor immunity and interfere with tumor development." (PMID 28927416, 2017). "As such, these results confirm an important additional role for IL-21 in promoting anti-tumour immunity." (PMID 28239749, 2017). "TH9 cells have an important role in tumor immunity that seems to be largely due to their ability to secrete IL-9 and IL-21 cytokines." (PMID 27832300, 2017). "Here, the authors show that, in both mice and humans, MHC-I downregulation is associated with the induction of NK-cell exhaustion and that IL-21 restores NK-cell function and inhibits tumours progression." (PMID 28585539, 2017). "Taken together, these results suggest that the functional exhaustion of Tim-3+PD-1+ NK cells in the tumour tissues of cancer patients can be restored by exogenous IL-21 treatment." (PMID 28585539, 2017). "Increased IL-21 levels, also produced by Th17 cells, can induce tumor regression through expansion of CD8+ tumor-infiltrating lymphocytes in NSCLC as well as ovarian cancer and melanoma." (PMID 27784305, 2016). "A systems biology approach aiming at quantifying different immune cell subpopulations in situ in human tumor found a positive correlation between IL-21 expression and disease-free survival." (PMID 27148488, 2016). "In the present study, we have shown that vaccination with tumor cells co-expressing IL-21 and IL-7 elicited potent antitumor responses in both prophylactic and therapeutic tumor models." (PMID 27571893, 2016). "Interleukin-21 pretreatment significantly extended survival of mice in a lymphoma model and blocked tumor metastasis in murine models of breast, lung, and prostate cancer." (PMID 27148255, 2016). "These facts suggested that CD4+ and CD8+ effector T cells were important participants in the antitumor immunity triggered by IL-21 and IL-7 co-expressing tumor cell vaccine, while NK cells are dispensable in such a process." (PMID 27571893, 2016). "IL-21 treatment prolonged persistence of endogenous and adoptively transferred tumor-specific transgenic CD8+ T cells, which was mainly attributed to IL-21-mediated promotion of survival." (PMID 27656185, 2016).
tumor (continued). "In this study, adjuvant activity of the IL-21 and IL-7 combination was tested in transplanted murine tumor models using lentivirally transduced whole-cell vaccines." (PMID 27571893, 2016). "In contrast, the administration of IL-15 and IL-21 in combination with CART cells in vivo increased their tumor killing capacity." (PMID 27409425, 2016). "These preliminary data suggested that vaccination with IL-21 and IL-7 co-expressing tumor cells exhibited good safety profile, with negligible, if any, side effect." (PMID 27571893, 2016). "Compared with WT controls, reduced tumor size and numbers were found in Il21−/− mice treated with AOM/DSS." (PMID 27148488, 2016). "As elucidated previously, CD4+ and CD8+ T cells take center stage in bolstering the antitumor immunity elicited by IL-21 and IL-7 co-expressing tumor cell vaccine." (PMID 27571893, 2016). "Combination of cytokines involving IL-21 demonstrated further enhancement of anti-tumor immunity compared to IL-21 as a monotherapy." (PMID 27656185, 2016). "Several preclinical studies showed that IL-21 has antitumor activity in different tumor models, through mechanism involving the activation of NK and T or B cell responses." (PMID 25961061, 2015). "As an example, a DNA vaccine encoding for IL-21 and IL-15 genes linked to the 47-LDA mimotope of disialoganglioside GD2, an antigen expressed mainly in NB, was particularly effective in inhibiting tumor growth in mice bearing NXS2 GD2+ NB." (PMID 25961061, 2015). "The effects of IL-21 on CTLs are well documented and important for its applications in tumor immunotherapy." (PMID 25961061, 2015). "In general, different IL-21-engineered tumor cells lose their tumorigenic potential in syngeneic mice through the induction of CTL and/or NK cell activation or B cell responses." (PMID 25961061, 2015). "Our data confirm and expand on our previous work showing up-regulation of IL-21 in the tumor areas of patients with sporadic CRC." (PMID 25839161, 2015). "CpG 2006 has been shown to upregulate IL21R in B CLL cells, leading to enhanced IL-21-mediated apoptosis of the tumor cells." (PMID 26158860, 2015). "The tumor tissues of IL-21 KO-Apcmin/+ mice exhibited reduced activation of STAT3/NF-kB and this was evident in both epithelial and immune cells." (PMID 25839161, 2015). "In view of the efficacy of IL-21 in preclinical studies of tumor immunotherapy, clinical trials of IL-21 as a single agent or in combination with other drugs were performed, in different cancers." (PMID 25961061, 2015). "These IL-2 and IL-21 exposed splenocytes, perhaps unsurprisingly, were the least efficacious at curing or slowing tumor growth." (PMID 25903148, 2015). "In some studies, IL-21-producing cells were used as a whole cell vaccine to treat mice previously challenged with wild type tumor cells." (PMID 25961061, 2015). "A similar method for the expansion of central memory-like (Tcm) TILs or T cells engineered to express a tumor-specific TCR is based on the use of IL-12 plus IL-7 or IL-21 followed by withdrawal of IL-12." (PMID 25961061, 2015). "DNA vaccination is another interesting approach to induce an antigen-specific immune response towards tumor cells or pathogens, whose effects can be enhanced by IL-21." (PMID 25961061, 2015). "The data indicate that IL-21 in the bone marrow microenvironment significantly affects the biology of WM tumor cells through a STAT3-dependent mechanism." (PMID 25590298, 2015). "As a key player within the integrated gene network, additional investigation is essential in order to better understand the complex role of IL-21 and its receptor on NK cell anti-tumor activity." (PMID 26470881, 2015). "Circulating Tfh cells in HCC patients were defective in the production of IL-21 in vitro, which was in accordance with lower IL-21 levels in tumor tissues than in para-tumor tissues." (PMID 26517519, 2015).
tumor (continued). "Although using IL-2 to stimulate the proliferation of anti-tumor T cells in culture remains the standard clinical approach, we were encouraged by our results with IL-7/15 to add or substitute IL-21 to our expansion regimen." (PMID 25903148, 2015). "Another cytokine, IL-21 coordinates colitis-associated tumorigenesis, leading to high IFN-γ and low IL-17A expression, which decreases tumor cell proliferation and increases tumor immunosurveillance." (PMID 25590298, 2015). "In early studies, IL-21 gene transfer has been used to generate cytokine-secreting tumor cells, in the attempt to trigger antitumor immune responses through a paracrine effect of IL-21." (PMID 25961061, 2015). "In contrast, IL-21 modulated the production of protumorigenic factors by human tumor infiltrating T cells." (PMID 25839161, 2015). "IL-17A produced by Th17 cells promotes tumor growth by inducing angiogenesis, while IL-21 produced by Th17 cells mediates antitumor effects including induction of apoptosis." (PMID 26478573, 2015). "In murine tumor models, IL21 induces a Th1 immune response and anti-angiogenic effects mediated by CXCL9 and CXCL10." (PMID 26305332, 2015). "IL-21 therapy in mice increases the number of tumor-infiltrating CD8+ T cells, expands the number of tumor-specific CD8+ T cells and protects the IL-21-treated mice against a recurrence of the same tumor." (PMID 24959288, 2014). "It has been shown that IL-21 promotes CD8+ T-cell dependent tumor responses against solid tumors in a mouse model." (PMID 24959288, 2014). "This phase 1/2 clinical trial evaluated the safety, anti-tumor activity, pharmacokinetic and pharmacodynamic effects of the combination of IL-21 with sorafenib in patients with mRCC." (PMID 24829759, 2014). "In our previous studies, interleukin-21 (IL-21) was involved in T and NK cell activation and induced a strong cell-mediated immune responses in the tumor vaccine approaches." (PMID 24444073, 2014). "Further analyses revealed that the downregulation of the IL-21 serum level was correlated with an increased tumor stage of DLBCL, while the expression of IL-21R on the CD8+ T cells was positively correlated with the tumor stage." (PMID 24959288, 2014). "These mice rejected subsequent GBM injections, and some mice with established GBM were salvaged by receiving IL-21-expressing tumor cells." (PMID 25505736, 2014). "IL-21 can exert potent anti-tumor effects due to its ability to induce and expand CD8+ CTLs and NK cells." (PMID 24782858, 2014). "In order to last the expression of IL-21 in tumor-bearing mice, we used lentiviral vector as delivery of IL-21 in this study." (PMID 24444073, 2014). "Previous studies have indicated that treatment with exogenous IL-21 enhances tumor infiltration and the cytotoxic function of effector CD8+ T cells in vivo." (PMID 25411639, 2014). "IL-7 synergizes with IL-12 or IL-21 to enhance anti-tumor immunity through the augmentation of cytotoxic T cells function." (PMID 24465710, 2014). "Further studies have shown that IL-21's effects on tumor protection were dependent on NKG2D-mediated recognition of tumor cells by NK cells." (PMID 25054077, 2014). "A negative correlation was also found between the serum level of IL-21 and the tumor stage, indicating the involvement of this cytokine in the progression of the disease." (PMID 24959288, 2014). "Studies have showed that IL-21 is widely applied to significantly augment antitumor immunity in multiple murine tumor models and clinical trials, and to generate considerable research interest in understanding its mode of action." (PMID 24625224, 2014). "Yet, other cytokines secreted by Th17 cells (IL-17F, IL-21, and IL-22) exhibit anti-angiogenic properties, convoluting the overall correlation between Th17 cell activity and tumor growth in the context of angiogenesis." (PMID 24987392, 2014).